ENSG00000280371 ( gene)
Diseases named in the same sentence as ENSG00000280371 in open-access papers (continued):
Sharing a sentence is not in itself a finding about the gene and the disease.
Alzheimer disease (1 paper, 2021). A progressive, neurodegenerative disease characterized by loss of function and death of nerve cells in several areas of the brain leading to loss of cognitive function such as memory and language. "Heterogeneous depletion of microglia Beclin1, another autophagy‐related gene, also affected microglia activation and neuroinflammation in Alzheimer's disease mouse model." (PMID 34811872, 2021).
anemia (1 paper, 2025). A reduction in the number of red blood cells, the amount of hemoglobin, and/or the volume of packed red blood cells. "In the current study, the upregulation of Fanconi anemia complementation group D2 (FANCD2) was identified, which is reported as a crosslink repair gene." (PMID 40428293, 2025).
arterial diseases (1 paper, 2021). "This indicated that a tobacco-smoking-related gene (CHRNA3) and a thrombosis-related gene (F5) might play an essential role in PAD but not in other arterial diseases." (PMID 34943774, 2021).
Arthritis (1 paper, 2022). Inflammation of a joint. "CRY1 is a circadian clock-related gene that also plays a part in arthritis." (PMID 35886000, 2022).
autosomal dominant retinitis pigmentosa (1 paper, 2008). Autosomal dominant retinitis pigmentosa (RP) is an autosomally dominant inherited retinal dystrophy leading to progressive loss of the photoreceptors and retinal pigment epithelium and resulting in blindness usually after several decades. "The purpose of this project was to determine if mutations, including large insertions or deletions, in the recently identified RP31 gene topoisomerase I-binding arginine-serine rich (RS) protein (TOPORS), cause an appreciable fraction of autosomal dominant retinitis pigmentosa (adRP)." (PMID 18509552, 2008).
beta thalassemia (1 paper, 2021). Beta-thalassemia (BT) is characterized by deficiency (Beta+) or absence (Beta0) of synthesis of the beta globin chains of hemoglobin (Hb). "In addition to the sickle trait gene (HBB), our mapping strategies identified other members of beta globin gene cluster that cause various forms of beta-thalassemia (HBE1, HBD, HBG, and HBG2)." (PMID 34868193, 2021).
Bohring-Opitz syndrome (1 paper, 2026). "Background/Objectives: ASXL1 is a chromatin-associated gene implicated in both hematologic malignancies and neurodevelopmental disorders, including Bohring-Opitz syndrome (BOS)." (PMID 41751615, 2026).
Breast fibroadenoma (1 paper, 2021). "Breast fibroadenoma (FA) and phyllodes tumour (PT) often have variations of gene mediator complex subunit 12 (MED12) and mutations in the telomerase reverse transcriptase promoter region (TERTp)." (PMID 33046803, 2021).
breast tumours (1 paper, 2006). "Though we have not confirmed tumour suppressor activity of SKCG-1, however, the loss of expression of SKCG-1 in highly proliferative human Wilms and breast tumours suggest that it is a potential growth regulatory gene." (PMID 16622458, 2006).
congenital neutropenia (1 paper, 2022). "Patients with severe congenital neutropenia (SCN) have mutations in the gene for jagged 1 protein, (JAGN1)." (PMID 36034717, 2022).
cutaneous melanoma (1 paper, 2025). A primary melanoma arising from atypical melanocytes in the skin. "Furthermore, DIRAS2 has been identified as a tumor suppressor gene in cutaneous melanoma by inhibiting the Wnt/β-catenin signaling pathway and is associated with immune infiltration." (PMID 40083697, 2025).
cyst (1 paper, 2015). A sac-like closed membranous structure that may be empty or contain fluid or amorphous material. "The morphants of ttc4 and ttc25, a known cilia-related gene, additionally showed pronephric cyst formation." (PMID 25860617, 2015).
diabetic retinopathy (1 paper, 2023). "Several studies have indicated Socs1 as an inflammatory suppressor gene in ocular disorders, including diabetic retinopathy and uveitis 60,61." (PMID 37063422, 2023).
diarrheal disease (1 paper, 2026). The condition of having at least three loose or liquid bowel movements each day. "METHODS: Herein, we assessed the molecular variability of the intimin virulence gene (eae) in EPEC isolates, recovered from children under 5 years in a case-control study of diarrheal disease in Manhiça, southern Mozambique, from 2007 to 2010." (PMID 41877076, 2026).
diffuse large B-cell lymphoma (1 paper, 2013). "Following multiple-testing correction, one SNP in MSH3, a mismatch repair gene, showed an association with diffuse large B-cell lymphoma (OR: 1.91; 95% CI: 1.41–2.59; uncorrected p = 0.00003; corrected p = 0.010)." (PMID 24098683, 2013).
Duchenne muscular dystrophy (1 paper, 2021). Duchenne muscular dystrophy (DMD) is a neuromuscular disease characterized by rapidly progressive muscle weakness and wasting due to degeneration of skeletal, smooth and cardiac muscle. "QKI-5 also regulates the expression of Duchenne muscular dystrophy gene (DMD) in skeletal muscle by promoting the inclusion of its muscle-specific exon." (PMID 34616743, 2021).
endometrial adenocarcinoma (1 paper, 2020). "Besides, Dae-Shik Suh and his colleagues reported that LRIG2 was a tumor suppressor gene in endometrial adenocarcinoma and inhibited cell growth through regulating PI3K/AKT and EGFR." (PMID 32863771, 2020).
endometrioid carcinoma (1 paper, 2023). "ARID1A, a tumor suppressor gene encoding BAF250, a protein participating in chromatin remodeling, is frequently mutated in endometrium-related malignancies, including ovarian or uterine clear cell carcinoma (CCC) and endometrioid carcinoma (EMCA)." (PMID 38071325, 2023).
ependymoma (1 paper, 2018). A WHO grade II, slow growing tumor of children and young adults, usually located intraventricularly. "We also found RAD51, another DNA repair gene, was up-regulated in supratentorial and infratentorial ependymomas." (PMID 29416789, 2018).
erythroleukemia (1 paper, 2021). Acute erythroid leukemia characterised by the presence of at least 50% erythroid precursors and at least 20% myeloblasts in the bone marrow. "Since FLI1 activation was frequently detected in erythroleukemias, it is therefore possible that this TF acts as an oncogene in erythroleukemias, but functions as a tumor suppressor gene in megakaryocytic leukemias." (PMID 33717090, 2021).
fibrosis (1 paper, 2017). the formation of excess fibrous connective tissue in an organ or tissue in a reparative or reactive process. "When RNA from kidney poles was analyzed, Grem1 levels were significantly increased in wild-type mice, consistent with previous data showing that Grem1 is a fibrosis-associated gene." (PMID 28100499, 2017).
follicular thyroid cancers (1 paper, 2020). "This contrasts to reports that NR4A3 acts as a tumor suppressor gene in lymphoreticular and follicular thyroid cancers." (PMID 32867110, 2020).
gastric MALT lymphoma (1 paper, 2022). "Although vacA is a potent immune gene, given the fact that this protein causes apoptosis, it does not appear to play a significant role in the development of gastric MALT lymphoma." (PMID 34980267, 2022).
gastric tumors (1 paper, 2016). "In this work, we identify GPC3 as a potential metastasis suppressor gene that controls cellular mechanisms of invasion and metastasis in gastric tumors." (PMID 27259271, 2016).
HCMV infections (1 paper, 2022). "HCMV infections were performed with a dual tagged Merlin HCMV strain which expresses mCherry linked to UL36 (an immediate early protein) and UL32-GFP fusion (pp150 a true HCMV late gene)." (PMID 36591233, 2022).
Hepatic steatosis (1 paper, 2015). Steatosis is a term used to denote lipid accumulation within hepatocytes. "Moreover, its antioxidant activities were also able to reduce the high cholesterol associated hepatic steatosis and inflammation through upregulation of the Bcl2a1a antiapoptotic gene." (PMID 26074993, 2015).
Hydrocephalus (1 paper, 2015). Hydrocephalus is an active distension of the ventricular system of the brain resulting from inadequate passage of CSF from its point of production within the cerebral ventricles to its point of absorption into the systemic circulation. "Recent studies have shown that the Lhx9 homeobox gene controls pineal gland development and prevents postnatal hydrocephalus." (PMID 26321920, 2015).
hypopharyngeal carcinoma (1 paper, 2023). Carcinoma, predominantly squamous cell, arising from the epithelial cells of the hypopharynx. "Similarly, in hypopharyngeal carcinoma, we found that KRT17 acts as a cancer suppressor gene; this effect may be related to the tissue specificity of KRT17." (PMID 36765563, 2023).
hypophosphatemia (1 paper, 2021). Lower than normal levels of phosphates in the circulating blood. "In contrast, hypophosphatemia enhances Nhdec2 expression in NPT2aKO osteocytes and phosphate treatment of Ocy454 cells decreases expression of this mineral resorption gene." (PMID 34043707, 2021).
idiopathic scoliosis (1 paper, 2019). A scoliosis with no known cause. "For example, a recent study reveals that the deficiency of a cilia-related gene, pkd2zko977a, in zebrafish embryos results in phenotypes similar to those of human idiopathic scoliosis." (PMID 31831591, 2019).
influenza (1 paper, 2016). An acute viral infection of the respiratory tract, occurring in isolated cases, in epidemics, or in pandemics; it is caused by serologically different strains of viruses (influenzaviruses) designated A, B, and C, has a 3-day incubation period, and usually lasts for 3 to 10 days. "Many studies on influenza pathogenesis in mice were performed in classical laboratory strains which carry a mutation in the influenza resistance gene Mx1 first described in the A2G mouse strain." (PMID 26921172, 2016).
invasive lobular carcinoma of the breast (1 paper, 2009). "In summary, our findings suggest that ADAM33 is a novel tumour suppressor gene that may be useful as a molecular marker for invasive lobular carcinoma of the breast." (PMID 19267929, 2009).
laryngeal squamous cell carcinoma (1 paper, 2025). A squamous cell carcinoma that arises from the larynx. "Additionally, as a tumor metabolic regulatory gene, SKA3 can inhibit the ubiquitination and degradation of polo-like kinase 1 (PLK1) protein, resulting in the upregulation of glycolytic enzymes and enhanced glycolysis in laryngeal squamous cell carcinoma." (PMID 41298345, 2025).
Lissencephaly (1 paper, 2022). A spectrum of malformations of cortical development caused by insufficient neuronal migration that subsumes the terms agyria, pachygyria and subcortical band heterotopia. "WDR47 (WD repeat-containing protein 47, MIM 615734), sharing structural homology with lissencephaly gene LIS1 (PAFAH1B1), participates in core microtubule-mediated processes, including neural stem cell proliferation, radial migration, and growth cone dynamics." (PMID 36277487, 2022).
lung neoplasm (1 paper, 2019). A benign or malignant, primary or metastatic neoplasm involving the lungs. "miRNAs have been found as a tumor suppressor gene and lung neoplasms." (PMID 31921290, 2019).
mismatch repair deficiency (1 paper, 2024). "The mismatch repair gene MSH3 has become a major focus for therapeutic development, as unlike other mismatch repair genes, nullizygosity for MSH3 does not cause malignancies associated with mismatch repair deficiency." (PMID 38387080, 2024).
multiple endocrine neoplasia type 1 (1 paper, 2010). An autosomal dominant tumor predisposition syndrome caused by pathogenic variants in the MEN1 gene, characterized by an increased risk of tumors of the parathyroid glands, pituitary gland, and foregut neuroendocrine tumors (most commonly pancreatic islet cells). "The multiple endocrine neoplasia type I gene functions as a tumor suppressor gene in humans and mouse models." (PMID 21124979, 2010).
multiple sclerosis (1 paper, 2023). A progressive autoimmune disorder affecting the central nervous system resulting in demyelination. "Multiple sclerosis is a fairly common autoimmune demyelinating disease; EVI5L may therefore play an important role in cellular immunity as an immune-related gene." (PMID 36635413, 2023).
myopia (1 paper, 2025). "With the progression of myopia, the proinflammatory macrophages and their expression of the hypoxia-responsive gene Car1 also increased gradually." (PMID 41330940, 2025).
neuritis (1 paper, 2016). A neuropathy arising from inflammation of one or more nerves. "It was also reported as a retinoic acid-responsive gene concerned with prenatal development and neuritis growth." (PMID 27571066, 2016).
ovarian serous carcinoma (1 paper, 2010). "RSF1, a chromatin-remodeling gene, was identified as a potential oncogene in ovarian serous carcinoma." (PMID 20932292, 2010).
pancreatic neuroendocrine tumor (1 paper, 2016). Pancreatic endocrine tumor, also known as pancreatic neuroendocrine tumor (PNET), describes a group of endocrine tumors originating in the pancreas that are usually indolent and benign, but may have the potential to be malignant. "Taken together, these observations demonstrate that CYR61 acts as a tumor-promoting gene in pancreatic neuroendocrine tumors." (PMID 26625209, 2016).
pituitary carcinoma (1 paper, 2020). A primary or metastatic malignant neoplasm affecting the pituitary gland. "In their study, they suggest that miR-17-5p is involved in pituitary carcinoma metastasis, attenuating target genes such as PTEN, a tumour suppressor gene, and TIMP2, involved in inhibiting the degradation of the extracellular matrix and basement membrane." (PMID 32316225, 2020).
prostate tumor (1 paper, 2021). "Transcriptomic profiling revealed a distinct gene expression profile of MCs isolated from prostate tumor regions, including the downregulation of SAMD14, a putative tumor suppressor gene." (PMID 33799802, 2021).
retinal diseases (1 paper, 2020). "Decidual protein induced by progesterone (DEPP) has been identified as a hypoxia-responsive gene that may be part of cellular pathways such as autophagy and connected to retinal diseases." (PMID 31963726, 2020).
T-cell acute lymphoblastic leukemia (1 paper, 2013). Acute lymphoblastic leukemia of T-cell origin. "In this chromosome locus, BCL11B may act as a tumor-suppressor gene in T-cell acute lymphoblastic leukemia." (PMID 24422944, 2013).
thymoma (1 paper, 2017). A neoplasm arising from the epithelial cells of the thymus. "In pTECs from thymomas, senescence became recognizable after 15 days in culture, and RNA expression of p16INK4A (a senescence-associated gene) started to rise progressively on day 10 to 15 after surgery and lasted till the 3rd to 5th passage." (PMID 29163772, 2017).
triple-negative breast carcinoma (1 paper, 2019). An invasive breast carcinoma which is negative for expression of estrogen receptor (ER), progesterone receptor (PR), and human epidermal growth factor receptor 2 (HER2). "Although decorin is regarded as the “endogenous guardian” and biglycan acts as a danger signal in cancer, asporin acts as an oncogene in some types of cancer (breast, pancreatic, colorectal, gastric, and prostate), but as a tumor suppressor gene in triple-negative breast cancer." (PMID 31608236, 2019).
tumor (793 papers, 1995 to 2026). "DAPK-1 is a tumor suppression gene and induces apoptosis in several cells associated in various diseases." (PMID 41189711, 2025). "Of note, although the proportion of trunk mutations was significantly less than branch mutations in L-FLAC patients, driver gene mutations (oncogene and tumor-suppression gene) were significantly enriched in trunk mutations (P = 0.038; Wilcoxon rank-sum test)." (PMID 38831114, 2024). "E-cadherin is a vital tumor development suppressor gene, and the loss of this protein adhesion can turn benign tumors into aggressive malignant tumors." (PMID 37762330, 2023). "The underlying mechanism is that TPM is a class II tumor-suppressor gene, and its gene sequence structure is complete, but its expression is insufficient or not expressed due to downregulation or silencing in transcription or translation." (PMID 37686101, 2023). "GSDMC was first discovered as a tumor‐associated gene in 2004, which is closely associated with melanoma metastasis." (PMID 37125240, 2023). "The retinoblastoma susceptibility gene (Rb1), as a tumor repressor gene, has critical effects on multiple cellular processes, such as ferroptosis, apoptosis, and DNA repair." (PMID 36851083, 2023). "KEAP1 is regarded as a tumor-suppressive gene, and research has shown that a KEAP1 loss-of-function mutation promotes tumor growth." (PMID 36909198, 2023). "For example, TSC2 (tuberous sclerosis complex 2) was a tumor suppression gene that was reported that specific mutations of this gene led to the development of renal and extra-renal tumors in mice." (PMID 37582720, 2023). "ccRCC represents 75% of all RCC cases, and about 80% of ccRCC cases harbor mutations of the tumour-suppressive gene, VHL." (PMID 35461314, 2022). "One of the PNenGs, IGF2R, was a tumor suppressor gene, with a high frequency of loss-heterozygosity (LOH) and protein expression in diverse types of malignant cancer." (PMID 34221990, 2021). "In fact, DUSP6 is implicated as a tumor suppressor gene in PC and, specifically, its expression is suppressed in MIA PaCa-2 cells through intron 1 hypermethylation." (PMID 34439102, 2021). "Authors concluded that Setd2 can potentially act as a tumor suppressor gene in lung adenocarcinoma, since its deficiency promoted shifting of the tumor grade." (PMID 34781949, 2021). "Although these data indicated Ctcf behaved as a tumor suppressor gene, which was also supported by somatic mutation burden of CTCF in a recent human pan-cancer study, contradictory results were seen in other models regarding the CTCF/MYC regulation axis." (PMID 31127282, 2019). "This is the first time PTEN has been directly connected with human B cell dysfunction outside of the cancer field where PTEN is a well-described tumor suppressor gene whose mutation or deletion plays a role in a variety of sporadic human cancers." (PMID 30792481, 2019). "In numerous contexts, miR-494 functions as tumor suppressor gene and has been linked to the induction of senescent phenotype in normal cells but in other contexts it correlates with tumor aggressiveness and progression." (PMID 29951371, 2018). "The OIS is a robust and sustained antiproliferative response brought by oncogenic signaling resulting from an activating mutation of an oncogene, or the inactivation of a tumor-suppressor gene." (PMID 29435113, 2018). "The chromatin modifier PRDM2/RIZ1 is inactivated by mutation in several forms of cancer and is a putative tumor suppressor gene." (PMID 29228717, 2017).